MMP2 (matrix metallopeptidase 2)
Diseases named in the same sentence as MMP2 in open-access papers (continued):
Sharing a sentence is not in itself a finding about the gene and the disease.
breast cancer (continued). "As discussed, MMP-2 contributes to each step of the breast cancer metastatic cascade by virtue of its ability to cleave a large repertoire of matrix and non-matrix substrates." (PMID 29874869, 2018). "These MMP-2-specific BMMPIs significantly reduced the growth of PyMT and 4T1 murine mammary cancer cell lines in bone by limiting TGFβ bioavailability compared to controls." (PMID 29874869, 2018). "Fibronectin affects other markers of EMT in breast cancer cells, upregulating the expression of N-cadherin, Snail, vimentin, and MMP-2." (PMID 30487436, 2018). "Taken together, these data suggest that MMP-2 activity is necessary for the successful metastasis of primary breast cancer cells to the secondary site." (PMID 29874869, 2018). "5-Aza treatment, as well as Dia treatment inhibited the MMP-2/9 expression in hypoxic breast cancer cells." (PMID 29695771, 2018). "After reaching the breast cancer cells, MMP-2 overpressed by cells hydrolyses gelatin layer to deshield PEG and switch on the function of HA." (PMID 29410811, 2018). "According to the literature, high metastatic lung cancer, rectal cancer and breast cancer are found to have high MMP-2 and MMP-9." (PMID 30558243, 2018). "Formononetin can also inhibit the migration and invasion of breast cancer cells by suppressing MMP2 and MMP9 through phosphoinositide 3-kinase/protein kinase B (PI3K–Akt) signaling pathways." (PMID 30092799, 2018). "For example, studies have shown that MMPs are expressed in feline tumors, including MMP9 and MMP2, in feline meningioma and mammary cancer, and MMP9 in feline lymphoma." (PMID 30104530, 2018). "Here, we provide further evidence that ALT-C binding to α2β1 integrin decreases MMP-9 and MMP-2 content in human breast cancer cells and decreases MMP-2 content in human microvascular endothelial cells (HMEC-1) by zymography." (PMID 29713337, 2018). "In breast cancer, MMP-2 levels/expression have been shown to correlate with poorer overall survival." (PMID 29874869, 2018). "In feline mammary carcinoma, the expression of MMP-2 in peripheral neoplastic foci of tumors with high histological grade (grade III) was higher than that in low-grade tumors." (PMID 29949618, 2018). "Down-regulation of p16INK4A promotes migration in breast cancer because of an increased secretion level of matrix metalloproteinase-2 (MMP-2)." (PMID 28412731, 2017). "Meanwhile, down-regulation of p16INK4A shows much aggressiveness in breast cancer cells by increasing the expression level of MMP-2." (PMID 28412731, 2017). "S100A15 binds directly to HER2 and regulates MMP2 to contribute to cell proliferation and invasion of breast cancer, respectively." (PMID 28498804, 2017). "MiR-519d suppresses trophoblast cell invasion and migration by downregulating MMP2, suppresses breast cancer by inhibiting STAT3 expression, and inhibits tumor metastasis and MMP2 expression in chondrosarcoma and osteosarcoma." (PMID 28146423, 2017). "The invasion and metastasis of HCC are closely related to tumor cell EMT, study has shown that the decrease in ALCAM expression was accompanied by a significant upregulation of MMP-2 expression in breast cancer." (PMID 29375378, 2017). "MMP-2 expression is contributed to matrix degradation and osteolytic bone metastasis in many tumors such as prostate cancer, breast cancer, and renal cell carcinoma." (PMID 28122633, 2017). "Our study provides initial evidence that, in addition to maintaining the integrity of ECM, TFPI-2 suppresses breast cancer cell invasion through the regulation of MMP-2 gene expression." (PMID 29051606, 2017). "EL suppressed adhesion, motility, and invasion of breast cancer cells by remodeling the actin cytoskeleton, downregulated gene expression of matrix metalloproteinases (MMP-2, −9, and −14), and inhibited FAK signaling." (PMID 28068967, 2017).
breast cancer (continued). "Pharmacological inhibition indicated that MMP2 release occurred through the activation of 5-LO in the breast cancer cells while addition of 5-HETE was shown to potentiate the effects of the breast cancer cell conditioned media." (PMID 28125014, 2017). "These experiments suggest that TFPI-2 decreases MMP-2 mRNA expression and subsequently the protein’s activity in breast cancer cells." (PMID 29051606, 2017). "Five of the twenty eight ceRNA hubs were common to all the four breast cancer subtype networks, including RECK, which controls breast cancer metastasis by regulating MMP-2 (matrix metalloproteinases-2) to inhibit tumor angiogenesis." (PMID 28052038, 2017). "Studies suggested that genes, such as MMP2, MMP9, MMP11 and uPA, were found to be associated with breast cancer progression, angiogenesis and metastasis." (PMID 28388580, 2017). "Studies have shown that EL inhibits breast cancer cell adhesion to ECM proteins, and inhibits breast cancer cell migration and invasion by reducing MMP-2, −9, and −14 mRNA expression." (PMID 28068967, 2017). "Malignant canine mammary tumours have been found to express higher levels of MMP2 than benign tumours or normal mammary tissue." (PMID 28531107, 2017). "Somiari and colleagues were able to detect elevated levels and activity of MMP-2 and MMP-9 in plasma from breast cancer patients, as well as in women determined to be high risk based on Gail Model predictions." (PMID 28228690, 2017). "Overexpression of WNT11 in EMSCs and BT-474 breast cancer cell lines resulted in higher MMP-2 and/or MMP-9 zymographic activities." (PMID 26861754, 2016). "As a consequence, increased expression of MMP2 and MMP9 have been associated with a more aggressive phenotype and poor prognosis in several solid tumors including breast cancer, ovarian carcinoma, head and neck squamous cell carcinoma and gastric cancer." (PMID 26979530, 2016). "Numerous studies have shown that MMP-2 is overexpressed in various human tumours, including breast cancer, lung cancer, colorectal tumours, pancreatic carcinoma, and gastric and esophageal cancers." (PMID 27051552, 2016). "Given that miR-204 decreases cellular levels of Rab40b in breast cancer cells, miR-204 would also be expected to inhibit MMP2 and MMP9 targeting to the forming invadopodia." (PMID 27789576, 2016). "Numerous studies have demonstrated overexpressed MMP-2 in various tumours: breast cancer, lung cancer, colorectal tumours, gastric and esophageal cancers, and pancreatic carcinoma." (PMID 27051552, 2016). "Aberrant MMP-2 and MMP-9 expression is apparent in breast cancers and these proteins release often associated with tumor invasion and metastasis." (PMID 26637807, 2016). "Impaired release was most obvious for MMP2, a proteinase with known functions in breast cancer invasion and metastasis." (PMID 27588391, 2016). "Highlighted Article: Rab40b plays a key role in mediating invadopodia function during breast cancer cell invasion by binding to Tks5 and functioning as a tether mediating MMP2 and MMP9 targeting to the extending invadopodia." (PMID 27789576, 2016). "Selenium has been shown to inhibit angiogenesis in 1-methyl-1-nitroso urea (MNU)-induced rat mammary tumors through the suppression of Vegf expression and inhibition of gelatinolytic activity of MMP-2." (PMID 27023566, 2016). "Overexpression of MMP-2 has previously been shown to promote both brain and bone metastasis in a preclinical model of breast cancer and to promote bone absorption in a prostate cancer model." (PMID 26667022, 2015). "The current study aims to gain a better insight into the impact of MMP-2 expression on survival and clinicopathological features of breast cancer patients using a meta-analysis." (PMID 25816052, 2015). "TIMP-2 was shown to promote breast tumor metastasis by regulating MMP-2-mediated breast cancer cell transmigration through lung microvascular endothelial cells." (PMID 26361584, 2015).
breast cancer (continued). "We found that RGD-stimulation of metastatic breast cancer cells upregulated the expression of MMP-2 and MMP-9." (PMID 28721370, 2015). "There were eight studies utilizing OS to assess the prognostic value of MMP-2 expression in breast cancer patients and four studies using DFS/RFS/DDFS as the indicator." (PMID 25816052, 2015). "AGPAT9 inhibits breast cancer invasion through, at least in part, up-regulating the activities of MMP-2 and MMP-9." (PMID 26110566, 2015). "The expression association between CD147 and MMP-2, MMP-9 has been well established in a series of human malignant tumors, such as gallbladder carcinoma, thyroid carcinoma, breast cancer, gastric cancer and colorectal cancer." (PMID 26507719, 2015). "Accordingly, an increased collagenase IV (MMP2, MMP9) activity has been linked to high tumor grades in breast cancer specimen and poor prognosis." (PMID 26674091, 2015). "While, there were other studies demonstrated that MMP-2 positivity was relevant to a poor prognosis in breast cancer, especially in postmenopausal patients with node-positive breast carcinoma." (PMID 26270045, 2015). "Matrix metalloproteinase 2 and 9 (MMP-2 and MMP-9) have been implicated as playing significant roles in enabling invasiveness and metastasis of breast cancer." (PMID 25885600, 2015). "Numerous studies have confirmed that increased expression of MMP-2 is positively correlated with the invasion and metastasis of human gastric cancer, colon cancer and breast cancer." (PMID 26005051, 2015). "Previous studies have reported that the MMP-2/-9 system plays a crucial role in breast cancer growth, invasion, and metastasis." (PMID 25698902, 2015). "(v) A reciprocal interaction exists between integrin β1 and MMP-2/MMP-9 in metastatic breast cancer cells." (PMID 28721370, 2015). "Increased MMP2 expression has been shown to predict adverse outcomes in patients with breast cancer." (PMID 25954957, 2015). "Matrix metalloproteinase 9 (MMP9) and Matrix metalloproteinase 2(MMP2) show a stronger expression in breast cancer tissue compared to that in normal breast tissue." (PMID 26674531, 2015). "Silencing KDM2A using small interfering RNAs increased the invasion and migration of breast cancer cells by suppressing a subset of matrix metalloproteinases, such as MMP-2, MMP-9, MMP-4 and MMP-15." (PMID 26430963, 2015). "A recent study with human breast cancer specimens established a correlation between MMP-2 and HIF-2α expression." (PMID 26305551, 2015). "As a result, this meta-analysis focuses on effects of MMP-9 and MMP-2 expression on prognosis for breast cancer." (PMID 26270045, 2015). "In the cell experiment, reduction of CHD1L inhibited the invasion and metastasis of breast cancer cells by mediating MMP-2 and MMP-9 expression." (PMID 26599012, 2015). "Given that a membrane type MMP (MT-MMP) plays a crucial role in the activation of pro-MMP-2 into matured-MMP-2 in breast carcinoma cells, the effect of ADC on MT-MMP expression was also examined." (PMID 25658913, 2015). "The malignant effect of MMP2 in tumour progression is established for melanoma, lung-, prostate-, colorectal, ovarian- and breast carcinoma." (PMID 26513020, 2015). "Silencing KDM2A with small interfering RNAs demonstrated increased invasion and migration of breast cancer cells by suppressing a subset of matrix metalloproteinases (MMP-2, -9, -14 and -15), as seen by real-time PCR." (PMID 25029110, 2014). "To assess the role of MMP-2 in Gα12QL-stimulated breast cancer cell invasion, we employed both genetic and pharmacologic suppression of the enzyme." (PMID 24976858, 2014). "NDRG2 also suppresses matrix metalloproteinase-9 (MMP-9) expression through the induction of BMP-4 secretion and inhibits NF-kappaB activity and MMP-2 and -9 secretion, which abrogates the metastatic potential of breast cancer and fibrosarcoma cells." (PMID 25061501, 2014).
breast cancer (continued). "In contrast, expression of a SUMO E3 ligase inactive mutant of PIAS1, owing to replacement of Cysteine 350 with serine (PIAS1 (CS)), enhanced TGFβ-induced activation of MMP2 in MDA-MB-231 breast cancer cells." (PMID 25594015, 2014). "It is known that fibronectin is capable of promoting the expression of MMP-2 in MCF7 breast cancer cells in culture." (PMID 25208219, 2014). "In order to confirm that these results were not restricted to the MCF7 tumor cell line, we analyzed the effects of FN treatment in MMP2 expression in the breast cancer cell line MDA-MB-436." (PMID 25208219, 2014). "An enhanced expression of MMPs, particularly the gelatinase (MMP-2 and MMP-9), is associated with high metastasis potential in several types of human carcinomas including breast cancer." (PMID 24618693, 2014). "Here, we report that expression of the SUMO E3 ligase PIAS1 suppresses TGFβ-induced activation of the matrix metalloproteinase MMP2 in human breast cancer cells." (PMID 25594015, 2014). "In an interesting study looking at bone specific metastasis in breast cancer, MMP-2 was found to be significantly overexpressed in bone as opposed to orthotopically located breast cells." (PMID 24670365, 2014). "To exclude the possibility that these results are restricted to MCF7 tumor cells, we analyzed the MMP2 promoter sequence in the MDA-MB-436 breast cancer cell line." (PMID 25208219, 2014). "Our study further investigated β1 integrin involvement in MMP-2 activation in response to Col I stimulation in breast cancer cells, and found it played an important role in this process." (PMID 25317077, 2014). "The finding that PIAS1 regulates TGFβ-induced MMP2 activation and invasiveness in breast cancer cells led us next to determine the role of PIAS1 in the invasive and metastatic behavior of breast cancer." (PMID 25594015, 2014). "Previous reports demonstrated that S1P induced MMP-9 expression in breast cancer cells and MMP-2 expression in endothelial cells." (PMID 25188412, 2014). "majorana inhibits breast cancer cell invasion by affecting the expression of MMP-2 and MMP-9, we decided to examine the protein expression level of MMP-2 and MMP-9 in the conditioned medium using OME-treated MDA-MB-231 cells." (PMID 23874773, 2013). "Cyclopamine also inhibited the invasive ability of both breast cancer cell lines by suppressing the expression levels of NF-κB, MMP2 and MMP9 protein." (PMID 23599805, 2013). "Among all MMPs, upregulation of MMP-2 and MMP-9 was shown to be associated with breast cancer metastasis and poor clinical outcome." (PMID 23874773, 2013). "Twist protein expression was detected in 151 (75.5%) of the breast cancer tissues, while the expression of MMP-2 and MMP-9 were detected in 194 (97.0%) and 192 (96.0%) specimens." (PMID 23935727, 2013). "Particularly in breast cancer, MMP2 and MMP9 have been shown to play a major role in cell migration and invasion and their enhanced levels in patients predicts poor clinical prognosis." (PMID 24098477, 2013). "Several results suggest that MMP-2 plays a key role in the brain metastasis formation of breast cancer cells, melanoma and leukemic cells." (PMID 23344048, 2013). "The inhibition of STAT3 by LLL12 also down-regulated the expression of known STAT3 target genes in ALDH+ breast cancer cells related to cancer cell proliferation, survival, and angiogenesis, including Cyclin D1, survivin, Bcl-2, Bcl-XL, MMP-2, and MMP-9." (PMID 24376586, 2013). "We found that MMP-3 was partially involved in astrocyte CM-induced breast cancer cell invasion but to a lesser extent compared with either MMP-2 or MMP-9." (PMID 24324647, 2013). "In breast cancer and melanoma cells, miR-340 and miR-34a lowered c-Met (an inducer of MMP-2 and MMP-9) and, thus, suppressed tumor cell migration and invasion." (PMID 23325049, 2013).
breast cancer (continued). "In fact, studies showed that inactivation of NFκB in MDA-MB-231 breast cancer cells inhibit the expression of many downstream target genes involved in tumor metastasis such as MMP-2, MMP-9, VEGF, ICAM-1 and uPAR." (PMID 23874773, 2013). "In this study COX-2 and MMP-2 produced by cerebral endothelial cells was found to facilitate the extravasation of breast cancer cells across the BBB." (PMID 23344048, 2013). "Overexpression of CSE1L in B16F10 melanoma cells and MCF-7 breast cancer cells stimulated invadopodia extension and matrix metalloproteinase-2 (MMP-2) secretion and increased the migration and invasiveness of the cancer cells." (PMID 23369209, 2013). "Because breast cancer and lung cancer WT cells are already expressing MMP-2 and MMP-9, and assuming RNA levels translates into active protein levels, these cells should be primed for invasion but they are not." (PMID 24324647, 2013). "TIMP-2 is a main negative regulator of MMP-2 enzyme activity and involved in several tumor metastasis processes, including breast cancer." (PMID 23533649, 2013). "The suppression of CD147 in breast cancer cells inhibited MMP2 and MMP9 production and cell invasion in vitro, while the invasive properties conferred on inflammatory cells by CypA are a result of MMP9 stimulation." (PMID 23031673, 2012). "HGF has also been shown to actively promote production of MT1-MMP in MDA-MB 231 cells, which further activated MMP2 and enhanced the invasiveness of breast cancer cells." (PMID 22242160, 2012). "Our studies show for the first time that an osteoblast derived proteinase, MMP-2, can significantly impact on tumor survival and establishment in the mammary tumor-bone microenvironment." (PMID 22238668, 2012). "Among the several MMPs previously related to breast cancer progression, the gelatinases (MMP-2 and MMP-9) stand out for their collagen type IV specific degradation capacity, in view of the fact that it is an abundant ECM component." (PMID 22260435, 2012). "The ERα coregulator (AIB1) amplified in breast cancer has been shown to promote breast cancer metastasis by activation of PEA3-mediated matrix metalloproteinase 2 (MMP2) and MMP9 expression." (PMID 22295247, 2012). "In this sense, high levels of MMP2, MMP3 and MMP9 proteins have been implicated in several malignancies including oesophageal, renal, head and neck, oral, colorectal, NSCLC, breast carcinomas and melanomas." (PMID 22455335, 2012). "Our findings suggest that MMP-9, MMP-2 and MT1-MMP, which are synthesized by epithelial cancer cells and cancer-associated fibroblasts, play an important role in malignant canine mammary tumors." (PMID 21726449, 2011). "Taken together, these findings indicate that Hsp90α and Hsp70 assist in MMP-2 activation, which increases breast cancer cell migration and contributes to breast cancer invasion." (PMID 21533148, 2011). "Other investigators have reported that α-mangostin exerts inhibitory effects on cell invasion and migration in mammary cancer cells due to downregulation of MMP-2 and MMP-9, and we cannot preclude that this mechanism was not operating in our study, as well." (PMID 21639868, 2011). "Despite the opposing results obtained for mRNA and protein expression in benign and malignant mammary tumors, a close relationship between MMP-2 and MT1-MMP was observed at the pre-transcriptional level." (PMID 21726449, 2011). "Our findings suggest a role for Hsp70 in MMP-2 activation, as well as in the migration and invasion of breast cancer cells." (PMID 21533148, 2011). "Together, these findings implicate Hsp70 as part of a co-chaperone complex that acts with Hsp90α in MMP-2 activation and contributes to breast cancer migration and invasion." (PMID 21533148, 2011). "Together, these findings support a model in which MMP-2 activation by an extracellular co-chaperone complex mediated by Hsp90α increases breast cancer cell migration and invasion." (PMID 21533148, 2011).